FGF9 (fibroblast growth factor 9)
Diseases named in the same sentence as FGF9 in open-access papers (continued):
Sharing a sentence is not in itself a finding about the gene and the disease.
multiple sclerosis (2 papers, 2019 to 2021). A progressive autoimmune disorder affecting the central nervous system resulting in demyelination. "In multiple sclerosis (MS) lesions, FGF9 has been demonstrated to act indirectly, i.e. via the initiation of a complex astrocytic response that compromises remyelination." (PMID 33860438, 2021). "FGF-9 has been known to be an inflammation promoter in multiple sclerosis." (PMID 31852428, 2019). "Various FGFs are elevated in autoimmune diseases of the brain, such as multiple sclerosis: FGF1 in remyelinated lesions, FGF2 in active lesions and in the cerebrospinal fluid, FGF9 in active demyelinated lesions, and FGF21 in activated microglia or macrophages." (PMID 33860438, 2021).
osteoporosis (2 papers, 2023 to 2024). A condition of reduced bone mass, with decreased cortical thickness and a decrease in the number and size of the trabeculae of cancellous bone (but normal chemical composition), resulting in increased fracture incidence. "As a previously proven loss-of-function mutation of Fgf9, we employed Fgf9S99N mutant mice, OVX-induced osteoporosis model, and cytodifferentiation assays to investigate the role of Fgf9 in regulating bone and fat balance in adult bone." (PMID 38993574, 2024). "This study underscores the crucial role of Fgf9 as a cytokine regulating the bone-fat balance in adult bone, suggesting that FGF9 is a potentially therapeutic target in the treatment of osteoporosis." (PMID 38993574, 2024). "More importantly, it is necessary to confirm the expression levels of FGF9 in correlation with the progression of osteoporosis in clinical studies involving elderly individuals and patients with senile osteoporosis." (PMID 38993574, 2024). "This study provides the first evidence that Fgf9 plays a critical role in the fate determination of BMSCs by facilitating adipogenesis and inhibiting osteogenesis, suggesting that FGF9 is a potential therapeutic target in the treatment of osteoporosis." (PMID 38993574, 2024). "Our results indicate that Fgf9 is involved in bone-fat imbalance of osteoporosis, which may be a new therapeutic strategy for patients with osteoporosis." (PMID 38993574, 2024). "Interestingly, the effects of Fgf9 on bone homeostasis are in line with the pathological manifestation characterized by a reduction in bone formation and an increased accumulation of BMAT in senile osteoporosis." (PMID 38993574, 2024).
Rhizomelia (2 papers, 2017 to 2025). Disproportionate shortening of the proximal segment of limbs (i.e. the femur and humerus). "FGF9−/− mice showed disproportionate shortening of the proximal skeletal elements (rhizomelia), which suggests that FGF9 promotes chondrocyte hypertrophy and vascularization of the cartilage anlagen." (PMID 29259709, 2017). "Mice lacking Fgf9 display rhizomelia, which is comparable to chondrodysplasia syndromes caused by activated FGFR3, and it has been revealed that FGF9 promotes hypertrophy of chondrocytes at early stages and regulates vascularization and osteogenesis at later stages in developing stylopod elements." (PMID 40256430, 2025).
synovial chondromatosis (2 papers, 2011 to 2024). Synovial chondromatosis is a type of non-cancerous tumor that arises in the lining of a joint. "Conversely, secondary synovial osteochondromatosis lacks FGF9 expression, implying a lower recurrence rate post-removal of loose bodies." (PMID 39486129, 2024). "In primary synovial osteochondromatosis, excess FGF9 in the synovial fluid induces chondrogenesis by residual mesenchymal stem cells, suggesting that simple removal of loose bodies might be insufficient." (PMID 39486129, 2024). "Distinguishing primary from secondary synovial osteochondromatosis involves differences in pathological features, proliferating cell nuclear antigen (PCNA) positivity rate in immunological testing, and fibroblast growth factor (FGF9) expression." (PMID 39486129, 2024).
abdominal aortic aneurysm (1 paper, 2022). Enlargement and ballooning of the vessel that supplies arterial blood to the abdomen, pelvis and legs. "FGF9 and NAV1 have been implicated in the abdominal aortic aneurysm and aortic valve stenosis respectively, which may indicate the observed calcification is systemic and not isolated to the abdominal aorta." (PMID 36277789, 2022).
Age-related cataract (1 paper, 2011). A type of cataract (opacification of the lens) that forms during the course of aging. "It will be useful for getting more insights into the role of Fgf9 signalling in lens development; moreover, our data suggest FGF9 as a candidate for human age-related cataracts." (PMID 21858205, 2011).
alveolitis (1 paper, 2022). "In contrast, we observed significantly more severe alveolitis in FGF9-OE lung sections at 6 dpi, characterized by a high number of infiltrating leukocytes, alveolar edema, and alveolar consolidation." (PMID 35675358, 2022). "Analysis of IAV tropism in FGF9-OE lungs at 1 dpi revealed a dramatic shift of infection into the alveolar space, which supported the severe alveolitis and alveolar edema we observed in FGF9-OE lungs at later time points." (PMID 35675358, 2022).
anorectal malformation (1 paper, 2019). "The study objective was to investigate the role of fibroblast growth factor 9 (Fgf9) in normal and anorectal malformation (ARM) embryos during the development of the anorectum." (PMID 31379938, 2019).
asthma (1 paper, 2024). "Our research showed miR-143-3p suppressed proliferation and migration of HASMCs through reducing the expression of FGF9, indicating the key role of FGF9 in the proliferation and migration of HASMCs in asthma." (PMID 38824534, 2024). "Besides, the expression of lncRNA MEG3/miR-143-3p/FGF9 in asthma patients and its correlation with clinical pathological parameters also need further clarification." (PMID 38824534, 2024). "FGF9 may play an important role in asthma through regulating the proliferation and migration of HASMCs." (PMID 38824534, 2024). "We established a cellular model of asthma by inducing human airway smooth muscle cells (HASMCs) with PDGF-BB, and detected levels of lncRNA MEG3, miR-143-3p and FGF9 in HASMCs through qRT-PCR." (PMID 38824534, 2024). "This study also did not further explore the effects of FGF9 alone on HASMCs and on the protective effect of lncRNA MEG3 on asthma." (PMID 38824534, 2024).
cardiomyopathy (1 paper, 2022). A disease of the heart muscle or myocardium proper. "Of relevance to the current study, FGF9 and FGF16, which belong to the same FGF9 subfamily as FGF20, play pivotal roles in protecting against cardiomyopathy." (PMID 35351862, 2022).
Cerebral ischemia (1 paper, 2023). Restriction of arterial blood supply to the brain associated with insufficient oxygenation to support the metabolic requirements of the tissue. "Fibroblast growth factor 9 (FGF9) was reported to exert a protective effect against myocardial damage and cerebral ischemia injury, but the impact of FGF9 in random flap survival is still unclear." (PMID 36769456, 2023).
chondrosarcoma (1 paper, 2024). A malignant cartilaginous matrix-producing mesenchymal neoplasm arising from the bone and soft tissue. "To investigate whether FGF4, FGF8, and FGF9 induce differential signaling via FGFR1c (referred to as FGFR1 here), we used rat chondrosarcoma (RCS) chondrocytes, an immortal chondrocyte cell line used to model proliferating chondrocytes in the developing limb." (PMID 38568193, 2024).
cleft lip (1 paper, 2021). Congenital defect in the upper lip where the maxillary prominence fails to merge with the merged medial nasal prominences. "The Fibroblast growth factor 9 (FGF9) mutation has been discovered in humans with cleft lip and palate." (PMID 33959039, 2021). "Furthermore, Fgf9 and Fgf18 have overlapping functions in skeletal development and they have been shown to interact in families with cases of cleft lip and palate." (PMID 33959039, 2021).
colorectal tumour (1 paper, 2010). "However, FGFR3-IIIc not only exclusively bind FGF18, but also FGFs 1, 2, 4, 8 and 9, among which FGF9 is expressed in colorectal tumour cells (data not shown)." (PMID 20234367, 2010).
coronary artery diseases (1 paper, 2024). "This insight suggests a correlation between FGF9 and the genetic basis of understanding coronary artery diseases." (PMID 39568660, 2024).
cyst (1 paper, 2023). A sac-like closed membranous structure that may be empty or contain fluid or amorphous material. "We focused on exploring the relationships between cyst cells and the other cell types, and we found that CDPC, PT, and the rest of the DCTs express Fgf9, which can bind to the Fgfr2 receptor in cyst cells; FGF9/FGFR2 interactions have been reported to induce cell proliferation." (PMID 37583898, 2023). "Furthermore, we found that the interaction of FGFR2/FGF9 in tubular cells and cyst cells may play an important role in the induction of cyst cell formation." (PMID 37583898, 2023). "In addition to FGFR2/FGF9, we also found that SPP1/CD44 interactions between immune cells, especially macrophages, and cyst cells may play an important role in the induction of cyst cell formation." (PMID 37583898, 2023).
dwarfism (1 paper, 2024). "Previously, it was described, that overexpression of Fgf9 in mouse chondrocytes leads to dwarfism phenotypes." (PMID 39129916, 2024).
epilepsy (1 paper, 2021). A brain disorder characterized by episodes of abnormally increased neuronal discharge resulting in transient episodes of sensory or motor neurological dysfunction, or psychic dysfunction. "A series of CKO mice (CKOVGAT mice, CKONestin mice, CKOVGLUT1 mice, CKOGFAP mice, CKOOlig2 mice, CKODAT mice, CKOMpz mice, and CKOChat mice) were generated to determine what type of cells knockout FGF9 is associated with the epilepsy in CKOOlig1 mice." (PMID 33608505, 2021). "Then depleting Fgf9 in different neural populations revealed that epilepsy was associated with GABAergic neurons." (PMID 33608505, 2021). "To determine whether epilepsy in CKOOlig1 mice is associated with GABAergic neurons, we generated a series of conditional Fgf9 knockout mice." (PMID 33608505, 2021). "To further investigate the molecular mechanism of Fgf9 CKO-induced epilepsy, we compared the gene expression profiles in the cortex of CKOOlig1 and control mice by RNA sequencing (RNA-seq)." (PMID 33608505, 2021). "Fgf9 deletion in CKOVGAT mice caused neuronal apoptosis and decreased GABA expression, leading to a GABA/Glu imbalance and epilepsy." (PMID 33608505, 2021). "Epilepsy in Fgf9 CKO mice is closely related to GABA/Glu imbalance, potentially caused by a decrease in the concentration of GABA29." (PMID 33608505, 2021). "To explore the involvement of FGF9 in epilepsy, we used a pentylenetetrazole (PTZ)-kindled mouse epileptic model and epileptic patients." (PMID 33608505, 2021). "Meanwhile, there was a good correlation between FGF9 and GABA in the serum, which strengthened the idea that Fgf9 loss-of-function causes an imbalance of GABA and Glu and induces epilepsy." (PMID 33608505, 2021). "FGF9 is widely expressed in the CNS, but very little is known about the impact of FGF9 on epilepsy." (PMID 33608505, 2021). "Thus, epilepsy in Fgf9 CKO mice is closely related to the imbalance in GABA/Glu, potentially caused by diminished concentration of GABA." (PMID 33608505, 2021). "Fgf9 deletion in GABAergic neurons caused neuronal apoptosis and decreased the expression of GABA by activating the adenylatecyclase (AC)/ cyclic AMP (cAMP) and extracellular signal-regulated kinase (ERK) signaling pathway, causing a GABA/Glu imbalance and inducing epilepsy in mice." (PMID 33608505, 2021). "Thus, FGF9 plays essential roles in GABAergic neuron survival and epilepsy pathology, which could serve as a new target for the treatment of epilepsy." (PMID 33608505, 2021). "In our study, epilepsy was found in FGF9 knockout in Olig1-postive progenitors rather than in Olig2-postive progenitors, which regulates the sequential specification of neural progenitor cells into motor neurons and oligodendrocyte precursor cells." (PMID 33608505, 2021).
focal seizures (1 paper, 2021). "The ROC analysis also indicated that FGF9 had a diagnostic efficiency for focal seizures with an AUC of 0.725." (PMID 33608505, 2021). "A receiver operating characteristic (ROC) curve with FGF9 was built to investigate the diagnostic value of serum FGF9 in focal seizures." (PMID 33608505, 2021). "The expression level of FGF9 in the serum of patients with focal seizures was significantly lower than that in controls (P value < 0.0001)." (PMID 33608505, 2021). "Furthermore, the decrease of FGF9 was commonly observed in serum of epileptic patients, especially those with focal seizures." (PMID 33608505, 2021).
glaucoma (1 paper, 2023). Increased pressure in the eyeball due to obstruction of the outflow of aqueous humor. "Cluster 2 also differentially expressed glaucoma gene CYP1B1, morphogen-encoding genes LEFTY2, FGF9, and FGF8." (PMID 37665325, 2023).
Glucose intolerance (1 paper, 2022). Glucose intolerance (GI) can be defined as dysglycemia that comprises both prediabetes and diabetes. "In contrast to the results obtained in AAV-shFGF9-infected DIO mice, Ad-FGF9 injection improves glucose intolerance as revealed by GTT experiments, and enhanced insulin sensitivity, as revealed by ITT experiments, and enhanced hepatic insulin signaling." (PMID 35517790, 2022). "Moreover, FGF9 transgene enhanced the insulin sensitivity and improved glucose intolerance in diet-induced obese FGF9alb-cre mice when compared to the control mice." (PMID 35517790, 2022).
gonadoblastoma (1 paper, 2018). A mixed germ cell/sex cord-stromal tumor characterized by the presence of large germ cells which resemble seminoma cells and small cells which resemble Sertoli or granulosa cells. "Risk of gonadoblastoma is high when the early stage of Sertoli cell differentiation is disrupted by mutations in SRY, WT1, SOX9, DMRT1, FOG2/GATA4, FGF9 etc.." (PMID 28825592, 2018).
Hallux valgus (1 paper, 2021). Lateral deviation of the great toe (i.e., in the direction of the little toe). "In this study, we explored the function of miR-182 and FGF9 in hallux valgus region bone tissue, and verified these findings in osteoblasts." (PMID 33456347, 2021). "Then we examined the mRNA levels of FGF family, FGF1, FGF4, FGF7, FGF8, FGF9 and found the high mRNA level of FGF9 in hallux valgus patients." (PMID 33456347, 2021). "We have demonstrated that miR-182 promotes the formation of bone by targeting FGF9, implicating an essential role of miR-182 in the etiology of hallux valgus." (PMID 33456347, 2021). "We have demonstrated for the first time that FGF9 is a novel target of miR-182 and that miR-182 promotes the formation of bone by targeting FGF9, implicating an essential role of miR-182 in the etiology of hallux valgus." (PMID 33456347, 2021). "Contrastingly, FGF9 levels were elevated in the hallux valgus patients relative to normal tissues." (PMID 33456347, 2021). "Investigating the regulation of FGF9 in hallux valgus may be useful for understanding the development and pathogenesis of this disease." (PMID 33456347, 2021).
hypophysis (1 paper, 2025). "qRT-PCR results indicated that the relative expression of FGF9 was higher in the hypophysis than in other tested tissues; the hypophysis plays a central role in regulating growth and metabolism." (PMID 40867703, 2025).
injury (1 paper, 2024). Damage inflicted on the body as the direct or indirect result of an external force, with or without disruption of structural continuity. "MiRNA182 was found to be decreased in the initial stage of acute nerve injury, allowing for essential inflammatory reaction and increased SC migration by targeting fibroblast growth factor 9 (FGF9) and Neurotrimin (NTM)." (PMID 38689881, 2024).
intestinal tumors (1 paper, 2011). "To assess the in-vivo significance of our analyses, we determined expression of FGF9 in specimen of mouse and human intestinal tumors." (PMID 21853123, 2011).
ischemia (1 paper, 2015). A hypoperfusion of the BLOOD through an organ or tissue caused by a PATHOLOGIC CONSTRICTION or obstruction of its BLOOD VESSELS, or an absence of BLOOD CIRCULATION. "In an ischemia hind limb model FGF-9 was found to target non-endothelial mesenchymal cell populations indicating that FGF-9 could also influence mesenchymal populations in the bone which could further lead to enhanced angiogenesis accompanied by increased osteoid formation." (PMID 25742620, 2015).
keloid (1 paper, 2020). An irregularly shaped, elevated mark on the skin caused by deposits of excessive amounts of collagen during wound healing. "In keloid scars, the levels of endogenous mTOR, phosphorylated mTOR, and p70S6K are elevated, which exerts a symbolic effect on the activation pathway of platelet-derived growth factor (PDGF) and fibroblast growth factor 9 (FGF-9)." (PMID 32742861, 2020).
maxillary deficiency (1 paper, 2025). "Here, we propose a two‐stage loop: high expression of FGF9 initiates maxillary deficiency, which in turn leads to insufficient mechanical unloading, exacerbating FGF9 upregulation and hindering maxillary growth." (PMID 40913526, 2025).
metabolic syndrome (1 paper, 2022). A cluster of metabolic risk factors for CARDIOVASCULAR DISEASES and TYPE 2 DIABETES MELLITUS. "Thus, targeting FGF9 might be exploited to treat nonalcoholic fatty liver disease (NAFLD) and metabolic syndrome." (PMID 35517790, 2022).
Miscarriage (1 paper, 2020). A pregnancy that ends at a stage in which the fetus is incapable of surviving on its own, defined as the spontaneous loss of a fetus before the 22th week of pregnancy. "Mapping of potential candidate genes at associated loci identified several genes (FGF9, TLE1, TLE4, E2F8, SIK1) with a plausible biological role in placental biology and miscarriage etiopathogenesis." (PMID 33239672, 2020).
neuroblastoma (1 paper, 2020). Neuroblastoma (NB) is the most common solid, extracranial childhood tumor. "The secretion of FGF9 can improve the survival rate and neurite growth of SH-SY5Y neuroblastoma cells." (PMID 32587563, 2020).
neuroendocrine tumors (1 paper, 2005). "In contrast to the suppression of apoptosis-related genes, FGF9, a growth promoting gene, was significantly increased in the neuroendocrine tumors." (PMID 15691381, 2005).
oesophagitis (1 paper, 2009). "Eosinophil-derived products in oesophagitis lead to increased FGF9 secretion by oesophageal epithelial cells." (PMID 18978176, 2009). "Patients with EoE have increased FGF9 in oesophageal mucosal biopsies, which correlates positively with alterations in histology known to occur with oesophagitis." (PMID 18978176, 2009). "Increased FGF9 is found in biopsies of EoE patients and may play a role in the pathogenesis of oesophagitis." (PMID 18978176, 2009). "The proliferative effects of FGF9 may then contribute to basal zone hyperplasia, a characteristic of oesophagitis." (PMID 18978176, 2009).
orofacial cleft (1 paper, 2019). A disorder of facial skeleton that is characterized by cleft lip and/or cleft palate that result in feeding, speech and hearing problems caused by failures during development. "For example, previous studies show that SNPs in the miRNA-binding sites of MSX1, FGF2, FGF5 and FGF9 are associated with the susceptibility of nonsyndromic orofacial clefts." (PMID 31122291, 2019).